CYP1A1 (cytochrome P450 family 1 subfamily A member 1)
Diseases named in the same sentence as CYP1A1 in open-access papers (continued):
Sharing a sentence is not in itself a finding about the gene and the disease.
Hypertension (30 papers, 2009 to 2025). The presence of chronic increased pressure in the systemic arterial system. "Elevated CYP1A1 activity enhances hypertension risk and Cyp1a1 gene polymorphisms have been linked to chronic kidney disease." (PMID 37791586, 2023). "Several of them (Ace, Comt, Cyp1a1, Glp1r, Hsd11b2, and Ren) are widely known as associated with hypertension development." (PMID 26821914, 2016). "We find that induction of hypertension in the cyp1a1-Ren2 TGR causes sustained activation of the thiazide-sensitive co-transporter by angiotensin II in the distal tubule." (PMID 22558431, 2012). "Previous studies in cyp1a1-Ren2 TGR have demonstrated that hypertension is associated with enhanced sodium reabsorption and the rise in blood pressure is aggravated by dietary sodium-loading." (PMID 22558431, 2012). "There is also evidence that induction of CYP1A1 is a risk factor for hypertension." (PMID 33050031, 2020). "Maternal exposure to TCDD, a dioxin, has been shown to induce hypertension in offspring through activation of the AhR/CYP1A1 axis and promotion of TH17-mediated renal inflammation." (PMID 41154514, 2025). "Cyp1a1-Ren2 transgenic mice are inserted with the Ren2 gene under the Cyp1a1 promoter and develop hypertension due to increased salt intake." (PMID 40144661, 2025). "In a maternal DEHP exposure model, low-dose RBE treatment significantly shielded adult rat offspring against hypertension, accompanied by a reduction in renal mRNA expression of CYP1A1 and ARNT." (PMID 38731818, 2024). "High blood pressure is observed in mice with a knockout of the Cyp1a1 gene or of the AhR gene; AhR is a regulator of CYP1A transcriptional activity." (PMID 39457686, 2024). "Activation of AhR and its downstream pathway have been reported to play a role in endothelium-dependent vascular dysfunction, hypertension, and cardiac hypertrophy inducing CYP1A1 expression and increasing ROS in the vasculature and heart." (PMID 35202128, 2022). "Nifedipine is a dihydropyridine L-type calcium channel blocker used to treat hypertension; its target gene (CACNA1S) and primary enzyme genes (CYP1A1 and CYP2A6) all had deleterious variants in our population." (PMID 35280256, 2021). "Our results showed DMB protected hypertension coinciding with the restoration of TCDD-induced increased CYP1A1 expression." (PMID 34578924, 2021). "We utilized the Cyp1a1‐Ren2 xenobiotic‐inducible transgenic rat model to mimic both the age of onset and rate of induction of hypertension observed in humans." (PMID 30916484, 2019). "In this study, we more closely model human hypertension onset by inducing blood pressure increases in the middle aged Cyp1a1‐Ren2 rat." (PMID 30916484, 2019). "Of note, the Cyp1a1‐Ren2 rat is well suited for the study of age‐related changes and hypertension since the model is based on the Fisher‐344 rat, a rodent model developed by the National Institute on Aging at the NIH." (PMID 30916484, 2019). "It has to be noted that induction of hypertension in Cyp1a1-Ren-2 transgenic rats is fully ANG II-dependent with exaggerated circulating as well as renal ANG II levels." (PMID 30054426, 2018). "We employed here inbred transgenic rats with inducible hypertension (strain name: Cyp1a1-Ren-2); these animals express the mouse Ren-2 renin gene under control of the Cyp1a1 promoter." (PMID 30054426, 2018). "The potential mechanism for this interaction was not very clearly, some studies have reported that both PPARG and CYP1A1 gene polymorphisms were associated with CAD related- risk factors, such as T2DM, obesity and hypertension, and so on." (PMID 28415751, 2017). "So, the decreased level of Cyp1a1 transcription in ISIAH renal cortex suggests its contribution to hypertension development in these rats." (PMID 26821914, 2016). "So, the decreased level of Cyp1a1 transcription in ISIAH renal medulla suggests its contribution to hypertension development in ISIAH rats." (PMID 28105926, 2016).
Hypertension (continued). "Renal data and plasma electrolytes in cyp1a1-Ren2 transgenic rats before and after the induction of hypertension." (PMID 22558431, 2012). "The current study was designed to resolve key mechanisms leading to hypertension in the cyp1a1-Ren2 TGR and focuses on sodium transport in the distal convoluted tubule." (PMID 22558431, 2012). "Experiments were performed in male Cyp1a1-Ren-2 transgenic rats with inducible hypertension." (PMID 37389123, 2023). "In view of that activation of the AHR/CYP1A1 axis can induce vasoconstriction, whether DMB antagonizes AHR/CYP1A1 to protect offspring against TCDD-induced hypertension deserves further clarification." (PMID 34578924, 2021). "To make the study even more relevant to the situation of patients already in the malignant phase of hypertension, we also examined if the treatment would attenuate hypertension and end-organ damage in our Cyp1a1-Ren-2 transgenic rats at the established malignant phase." (PMID 30054426, 2018). "In young Cyp1a1-Ren2 rats AT1R activation leads to induction of an immune response, causing a shift from Th1-cells to Tregs, contributing to the development of irreversible renal damage and hypertension." (PMID 23469072, 2013). "In contrast, when induction is aimed at producing a non-malignant stable hypertension, chronic amiloride treatment causes a transiently negative sodium balance and abolishes hypertension in cyp1a1-Ren2 TGR, even though ENaC mRNA levels do not change." (PMID 22558431, 2012). "BPA is likewise an AhR agonist, with prenatal exposure leading to offspring hypertension accompanied by increased renal expression of AhR, AHRR, CYP1A1, and ARNT." (PMID 41154514, 2025). "Is GPR75 downstream of CYP1A1 also affected by high levels of Hcy, and through what mechanism does GPR75 participate in the occurrence of hypertension?" (PMID 40649725, 2025). "Maternal exposure to the AHR ligand TCDD induces hypertension in offspring, correlated with AHR/CYP1A1 induction and TH17-mediated renal inflammation." (PMID 38731818, 2024). "In a rat model of maternal BPA exposure, adult offspring developed hypertension alongside increased protein levels of AHR and mRNA expression of AHRR, CYP1A1, and ARNT in the offspring kidneys." (PMID 38731818, 2024). "Two decades ago, new strain of inbred transgenic rats with inducible hypertension [strain name, TGR (Cyp1a1–Ren-2)] was generated using the cytochrome P-450 promoter, Cyp1a1, to regulate the expression of the mouse Ren-2 renin gene." (PMID 37389123, 2023). "We observed that high-dose RBE that protected offspring against hypertension coincided with decreased renal expression of ARNT and AHR downstream of the target gene CYP1A1." (PMID 36771404, 2023). "Recently, inbred transgenic rats with inducible hypertension [strain name, TGR (Cyp1a1–Ren-2)] have been generated using the cytochrome P-450 promoter, Cyp1a1, to regulate the expression of the mouse Ren-2 renin gene." (PMID 34122103, 2021). "The aim of the present work was to quantify the mRNA expression of genes CYP1A1, CYP1B1, and CYP2J3 in different regions of the heart and in the aorta and to assess a possible contribution of expression changes to the development of hypertension." (PMID 39457686, 2024). "RCC risk has been found to be associated with interactions between alcohol consumption and ADH726; sodium and hypertension and AGTR, AGT and ACE31; calcium and vitamin D intake and RXRA28; tobacco smoking and NAT2, CYP1A1 and GSTM125; and meat-cooking mutagens and ITPR2 and EPAS127." (PMID 31924838, 2020). "The Cyp1a1‐Ren2 rat model has not previously been used to study the effects of hypertension on cognition." (PMID 30916484, 2019). "Considering that the activation of the AHR/CYP1A1 axis can induce vasoconstriction, RBE suppressed renal ARNT/CYP1A1 expression might, at least in part, contribute to its beneficial actions against DEHP-primed hypertension." (PMID 36771404, 2023).
Hypertension (continued). "Considering activation of the AHR/CYP1A1 axis induces vasoconstriction, resveratrol suppress renal CYP1A1 expression might, at least in part, contribute to its beneficial effects against TCDD-induced hypertension." (PMID 34573025, 2021). "One such model is the cyp1a1-Ren2 transgenic rat (TGR) in which hypertension can be reversibly induced, without surgical intervention, by dietary administration of the non-toxic, naturally occurring (for example in brassicas) aryl hydrocarbon, indole-3-carbinol (I3C)." (PMID 22558431, 2012).
colorectal cancer (27 papers, 2010 to 2025). A primary or metastatic malignant neoplasm that affects the colon or rectum. "The association between CYP1A1*2C and colorectal cancer has been investigated in many studies; however, the results are controversial." (PMID 39769254, 2024). "Second, compared with younger people, older people showed a stronger interaction between CYP1A1 genetic variants and flavonol intake with regard to colorectal cancer risk, possibly because of a greater effect of the environmental factors." (PMID 28273931, 2017). "In conclusion, the effect of dietary flavonoid intake on colorectal cancer risk differs according to flavonoid subclasses and CYP1A1 genetic variants." (PMID 28273931, 2017). "In this study, the CYP1A1 genetic variant was suggested to play a role in the etiology of colorectal cancer." (PMID 28273931, 2017). "Numerous individual case-control studies have investigated the associations between the CYP1A1 rs1048943 A > G and rs4646903 T > C genetic variations and colorectal cancer (CRC) risk, but the conclusions were controversial." (PMID 27384991, 2016). "They found a statistically significant relationship between CYP1A1 Ile462Val minor allele and increased risk of colorectal cancer (recessive model: OR 1.45, 95 % CI 1.16–1.81)." (PMID 24939416, 2014). "Recently, two meta-analyses, done by Jin (2011) and Zheng (2012), concerning CYP1A1 Ile462Val polymorphism and its role in colorectal cancer risk have been published." (PMID 24939416, 2014). "Only one of the studied SNPs, the CYP1A1 Ile462Val variant (minor allele), emerged as a single-putative risk allele in sporadic colorectal cancer patients especially for female over 50 years old." (PMID 24939416, 2014). "Similar results were reported in colorectal cancer where heterozygous and variant genotypes of both CYP1A1*2A and CYP1A1*2C conferred risk in combinations with NAT2 only among non-smokers." (PMID 22206016, 2011). "An 8-fold increased risk of colorectal cancer among Japanese homozygotes of CYP1A1*2A allele in Hawaii is probably a chance finding due to small numbers (23 cases and 59 controls)." (PMID 20534171, 2010). "CYP1A1*2C was unrelated to colorectal cancer risk in these studies, but was associated with an increased risk in another study." (PMID 20534171, 2010). "While multiple studies have shown that CYP1A1 genetic polymorphisms (CYP1A1 Msp I and CYP1A1 Ile/Val) could be risk factors for esophageal, gastric, and colorectal cancers, the current data remain controversial." (PMID 33659048, 2021). "Individuals with different CYP1A1 variants might experience a different benefit from the intake of certain dietary flavonoid subclasses on the prevention of colorectal cancer." (PMID 28273931, 2017). "Third, unhealthy lifestyle habits, such as physical inactivity, smoking and alcohol consumption, might increase the interaction between flavonol intake and CYP1A1 polymorphisms with regard to colorectal cancer risk." (PMID 28273931, 2017). "As shown in the present study, the rs4646903 variant may be associated with a reduced risk of colorectal cancer; thus, CYP1A1 may be involved in detoxification." (PMID 28273931, 2017). "Partial meta-analyses on the association of CYP1A1 polymorphisms and colorectal cancer risk showed that CYP1A1 rs1048943 A > G might be associated with increased risk of CRC." (PMID 27384991, 2016). "They concluded that CYP1A1 Ile462Val polymorphism may contribute to colorectal cancer risk in Asians as well as Europeans." (PMID 24939416, 2014). "People with high circulating hexanal blood levels, leading to a higher CYP1A1 expression, may thus be at higher risk of developing a colorectal cancer, as was demonstrated for genetic polymorphisms increasing CYP1A1 expression or activity." (PMID 21304969, 2011). "Therefore, we examined whether greater dietary intake of flavonoid subclasses was associated with a lower risk of colorectal cancer and whether CYP1A1 genetic variants altered this association." (PMID 28273931, 2017).
colorectal cancer (continued). "Mechanistically, we found that BOLD-100 acutely upregulates CYP1A1 mRNA and ROS levels, particularly in colorectal cancer cells, with activated BRAF oncogene." (PMID 39083088, 2024). "Examples are Phortress, a synthetic CYP1A1 activated prodrug, currently undergoing phase-I trial, with potent activity against breast and colorectal cancer and resveratrol, a CYP1B1 activated cancer-preventative prodrug." (PMID 26580399, 2015). "Of the gene-gene interactions studied, the composite genotype of CYP1A1*2A or CYP1A1*2C and GSTT1 polymorphisms was associated with a decreased risk of colorectal cancer, showing a nearly statistically significant (Pinteraction = 0.06) or significant interaction (Pinteraction = 0.02)." (PMID 20534171, 2010). "The present findings showed neither an increased risk of colorectal cancer in relation to the composite of CYP1A1 variant allele and NQO1 187Ser alleles nor an interaction between the composite genotypes and smoking." (PMID 20534171, 2010). "The composite genotype of GSTT1 non-null and CYP1A1*2A or CYP1A1*2C allele was associated with a decreased risk of colorectal cancer." (PMID 20534171, 2010). "Thus, rs1048943 allele variants in the CYP1A1 gene represent the risk of developing the most common malignancies, both regardless of population origin (colorectal cancer) and for certain regions and specific ethnic groups." (PMID 36553620, 2022). "The CYP1A1 locus was reported previously as risk modifier for Lynch syndrome colorectal cancer, although data were not confirmed in independent studies and common variants in CYP1A1 and in other genes controlling the estrogen metabolism have been associated with sporadic endometrial cancer." (PMID 26517685, 2015). "Mechanistically, our study showed that the AhR controls BOLD-100 induced CYP1A1 levels, ROS production, and ATR activation in BRAFMT colorectal cancer cells." (PMID 39083088, 2024). "There was no measurable interaction between CYP1A1 and NQO1 polymorphisms in relation to colorectal cancer risk." (PMID 20534171, 2010). "Although Hutu-80 cells are derived from the small intestine, unlike in the large intestine cancer-derived cell lines, the expressions of CYP1A1, CYP1A2, CYP2C9/10, and CYP3A could not be detected also in Hutu-80 cells." (PMID 34604364, 2021).
cervical carcinoma (20 papers, 2012 to 2025). A carcinoma arising from either the exocervical squamous epithelium or the endocervical glandular epithelium. "The Cox multivariate regression results further indicated that high expression of AHR and CYP1A1 was a risk factor for the prognosis of patients with cervical cancer." (PMID 34784845, 2021). "The Cox multivariate regression showed that high expression of AHR (HR = 1.874, 95% CI = 1.069–3.285, P= 0.028) and CYP1A1 (HR = 1.822, 95%CI = 1.077–3.080, P= 0.025) were risk factors for prognosis in patients with cervical cancer." (PMID 34784845, 2021). "Studies by several scholars have shown that polymorphic variants in the CP450 family gene CYP1A1 can increase the risk of cervical cancer, especially in Asians." (PMID 34796111, 2021). "We evaluated the association between four common polymorphisms in the human CYP1A1 and development of cervical cancer among Northeastern Thai women." (PMID 31983191, 2020). "Our aim was thus to evaluate these four polymorphic loci of CYP1A1 for the cervical cancer susceptibility among Northeast Thai women." (PMID 31983191, 2020). "In summary, our results demonstrated the possible involvement of the CYP1A1 m4 polymorphism over against other common polymorphisms (m1, m2, and m3) in the risk for cervical cancer among Northeast Thai women." (PMID 31983191, 2020). "A recent meta-analysis that included 98 publications reporting genetic association studies of SNPs with risk to cervical cancer in Indian women revealed that only rs1048943 of CYP1A1 to be significantly associated with cervical cancer." (PMID 31337018, 2019). "Recently, the relationships between some other polymorphisms and cervical cancer development were investigated, such as CYP1A1 MspI (rs4646903), COMT (rs4680), and CYP2E1 (rs3813867) polymorphisms." (PMID 29326607, 2017). "After data syntheses, we found a borderline correlation of CYP1A1 Ile462Val polymorphism with the susceptibility to cervical cancer in total analysis." (PMID 29326607, 2017). "A few meta-analyses were also conducted to figure out the influence of CYP1A1 Ile462Val polymorphism on cervical cancer susceptibility." (PMID 29326607, 2017). "Characteristics of previous published meta-analyses on CYP1A1 Ile462Val polymorphism and cervical cancer risk." (PMID 29326607, 2017). "Meta-analysis results on the relationship of CYP1A1 Ile462Val polymorphism with cervical cancer risk." (PMID 29326607, 2017). "The results showed that evidence of the effect of CYP1A1 Ile462Val polymorphism on cervical cancer incidence was stable during the cumulative meta-analysis, but the CIs became increasing narrower." (PMID 29326607, 2017). "The total analysis revealed a borderline relationship between CYP1A1 Ile462Val polymorphism and cervical cancer risk in general population." (PMID 29326607, 2017). "In summary, our meta-analysis outcomes revealed a borderline relationship between CYP1A1 Ile462Val polymorphism and cervical cancer risk in general population, and this polymorphism significantly increase the risk in Caucasian females." (PMID 29326607, 2017). "On one hand, individuals carrying the TC genotype were 2.29-fold at a higher risk for developing cervical cancer compared with those having homozygous association of CYP1A1 CC&TT genotypes (OR = 2.29, 95% CI = 1.25–4.20, p = 0.007)." (PMID 26798414, 2016). "The lower activity of COMT represents a higher risk for cervical cancer and so does the highest activity of CYP1A1." (PMID 26798414, 2016). "The highest risk for cervical cancer was for the association of CYP1A1&COMT TC&HL (OR = 6.07, 95% CI = 1.67–22.09, p = 0.006), without adjusting for age." (PMID 26798414, 2016). "In the current study, it was shown that women with cervical cancer have the genotypes of CYP1A1 M1 TC&CC, which represented almost 3-fold risk when associated to CYP1A1 CC genotype, in a dominant model." (PMID 26798414, 2016).